GFAP (glial fibrillary acidic protein)
Diseases named in the same sentence as GFAP in open-access papers (continued):
Sharing a sentence is not in itself a finding about the gene and the disease.
glioma (continued). "The lack of nestin/GFAP expression changes in human primary glioblastoma cells implicates no induction of cell differentiation by the treatments, although such responses have been described for 5-aza-dC in hypermethylated IDH1-mutant secondary gliomas." (PMID 31639020, 2019). "Indeed, glioma stem-like cells expressed RPS27, which was independent of GFAP or Ki67 positivity." (PMID 32349320, 2020). "NG2, a chondroitin sulfate proteoglycan, is expressed by oligodendrocyte progenitors, and identification of one type of GFAP-negative/NG2-positive astrocytes in adult normal brain and a subset of gliomas led to a hypothesis that certain gliomas arise from the NG2-positive progenitor cells." (PMID 16623952, 2006).
Stroke (405 papers, 2007 to 2026). Sudden impairment of blood flow to a part of the brain due to occlusion or rupture of an artery to the brain. "Whereas the patients with stroke lesions presented a significant association only between GFAP and cognitive decline (p = 0.0011)." (PMID 40076944, 2025). "And which suggests that GFAP upregulation is linked to the proliferative response of astrocytes, contributing to neural plasticity and functional recovery after stroke." (PMID 41254768, 2025). "While GFAP shows promise as a diagnostic tool for optimizing stroke management in acute settings, further research is necessary to address unresolved variations in findings." (PMID 40142325, 2025). "In summary, our data demonstrated that higher serum levels of GFAP are associated with increased risk of cognitive impairment measured at 90-days after stroke." (PMID 40421099, 2025). "This is concerning since elevated GFAP levels are associated with central nervous system damage and stroke risk is increased by type 2 diabetes, which further exacerbates the problem." (PMID 41150802, 2025). "GFAP levels can be used as an indicator of the extent of brain damage and can also be used to distinguish between stroke types and a stroke from other causes." (PMID 41150802, 2025). "Higher GFAP levels have also been associated with increased stroke severity and a history of previous stroke, suggesting a link between elevated GFAP and both acute and chronic neurological/brain injury." (PMID 41227149, 2025). "In fact, based on NIHSS values, GFAP has better diagnostic performance in patients with NIHSS scores above the median of 14 who have more severe stroke symptoms." (PMID 38891912, 2024). "This suggests that GFAP can be a useful biomarker for predicting long-term disability contributing to patient risk stratification and eventually leading to a tailored post-stroke care." (PMID 39459548, 2024). "In case of predicting short-term outcomes (supplement), both serum NfL and GFAP demonstrate associations with early clinical and radiological measures of stroke severity." (PMID 38400734, 2024). "We used an adeno-associated virus to deliver Neurod1 from the short GFAP promoter and demonstrated improved functional outcomes as early as 28 days post-stroke and persisting to at least 63 days post-stroke." (PMID 38540276, 2024). "Although a positive interaction was found between prior stroke and sGFAP levels, the presence of a prior stroke was associated with lower GFAP levels." (PMID 39777311, 2024). "First, the diagnostic accuracy of GFAP in recognizing intracranial haemorrhage was evaluated in 135 stroke patients (42 ICH, 93 IS) within six h of symptom onset." (PMID 37511304, 2023). "In the late stage of post-stroke, astrocytic morphological changes are associated with the upregulation of GFAP, which is called reactive astrogliosis." (PMID 37464832, 2023). "S100β, neuron-specific enolase (NSE), and glial fibrillary acidic protein (GFAP) have been reported to be associated with the pathophysiology of stroke and traumatic brain injury." (PMID 37098084, 2023). "The diagnostic performance of both symptom-based stroke scales and GFAP tends to increase as the inclusion of patients becomes increasingly selected." (PMID 36604741, 2023). "The difference was that our study distinguished multiple time points, as the circulating level of GFAP underwent obvious perturbation following time after stroke onset, which affected diagnostic performance substantially." (PMID 37762122, 2023). "GFAP levels are associated with stroke severity, infarct volumes, bleeding volumes, and stroke location." (PMID 36604741, 2023). "Glial fibrillary acidic protein was eligible for diagnostic meta-analysis, with summary sensitivities and specificities for differentiating HS from IS between 3 h and 24 h after stroke onset ranging from 73% to 80% and 77% to 97%, respectively." (PMID 37762122, 2023).
Stroke (continued). "Adding biomarkers (GFAP and D-dimer) to a prehospital stroke scale was associated with a high AUC of 0.95 (95% CI 0.91–1.00)." (PMID 36604741, 2023). "In neuro-inflammatory conditions such as stroke, astrocyte hypertrophy has been associated with GFAP intermediary filament production used as a marker of reactive astrocytosis." (PMID 35624723, 2022). "Associations of NF-L, tau, and/or GFAP levels with the severity of brain damage or brain atrophy have also been found in conditions such as traumatic brain injury, stroke, Alzheimer’s disease, and old age9,16,23,58,59." (PMID 33558486, 2021). "This is in contrast to a wide range of other CNS pathologies, such as stroke and glioblastomas, which are associated with reactive astrogliosis with increased astrocyte proliferation and GFAP levels." (PMID 34503077, 2021). "In a study presented by Hol and colleagues states that astrocyte reactive (astrogliosis) causes overexpression of GFAP which can be found in various CNS diseases such as spinal cord injury, stroke and neurodegenerative diseases such as spondylotic myelopathy." (PMID 34429942, 2021). "Several studies have found an acute increase in serum or plasma GFAP after intracerebral hemorrhage and an association between serum GFAP and stroke severity or stroke volume." (PMID 33678186, 2021). "Specifically, compared to the non-stroke control cortex (top row), ET-1 injection caused significant tissue damage as revealed by immunostaining of NeuN, GFAP, and Iba1 at 3 weeks after focal ischemic stroke (bottom row)." (PMID 33224952, 2020). "Higher plasma levels of NfL and GFAP were associated with any stroke (odds ratio 2.02, 95% confidence interval [CI] 1.06–3.87) and ICH (odds ratio 2.06, 95% CI 1.26–3.35) at baseline, respectively." (PMID 32321529, 2020). "After adjusting for age, sex, and hypertension, the higher NfL level was found to be associated with any stroke at baseline (aOR 2.02, 95% CI 1.06–3.87, p = 0.03), whereas the GFAP level had a borderline association (aOR 2.51, 95% CI 0.92–6.89, p = 0.07)." (PMID 32321529, 2020). "We added all relevant neuroimaging variables and applied a stepwise selection method, and the results remained consistent, that is, NfL was associated with stroke (OR 2.12, 95% CI 1.08–4.18), and GFAP was associated with ICH (OR 1.87, 95% CI 1.00–3.52)." (PMID 32321529, 2020). "PEG-IGF-I appears to act on post-stroke reactive astrogliosis when given early (3 hrs post-stroke) by increasing GFAP expression, a hallmark of reactive astrogliosis." (PMID 28325900, 2017). "Co-labeling with NeuN and GFAP demonstrated considerable loss of neurons and abundant hypertrophic reactive astrocytes in the ipsilateral thalamus in the Stroke/vehicle group." (PMID 29247238, 2017). "An intriguing observation arising from these analyses is that ‘history of previous stroke’ was independently associated with higher GFAP concentrations after acute ischemic stroke." (PMID 27074724, 2016). "Our results demonstrate that blood UCH-L1 and GFAP are increased early after stroke and distinct biomarker-specific release profiles are associated with stroke characteristics and type." (PMID 27074724, 2016). "Elevated serum GFAP can provide diagnostic and prognostic information in a range of neurological diseases including neurodegenerative disorders, stroke, and severe TBI." (PMID 26455520, 2015). "Several case-control studies showed that blood levels of S100B, NSE and GFAP are elevated in acute stroke, and are associated with poor stroke outcome." (PMID 23497639, 2013). "The up-regulation of intermediate filament proteins, such as GFAP, is a hallmark of reactive astrogliosis, including glial scar formation bordering the infarct core after stroke." (PMID 21714902, 2011). "This supports the notion that elevated GFAP reflects astrocyte activation and neurovascular injury that may underlie both cognitive decline and increased stroke risk in dysglycaemic states." (PMID 41296388, 2025).
Stroke (continued). "However, the biosensor results also demonstrate the possibility of a robust, specific analysis of additional markers such as glial fibrillary acidic protein, suggesting the potential of a multiplex stroke panel for even greater diagnostic accuracy." (PMID 40277577, 2025). "However, the lack of replication across multiple independent studies highlights the need for further research to validate GFAP’s diagnostic and prognostic utility in diabetic populations at risk for stroke or neurovascular complications." (PMID 41150802, 2025). "As part of the differential diagnosis, GFAP has demonstrated promising diagnostic accuracy in distinguishing ICH not only from ischemic stroke but also from stroke mimics, as its concentration is significantly elevated in patients with ICH compared to those with AIS." (PMID 41227149, 2025). "NR2 and GFAP are brain-specific markers associated with stroke." (PMID 39001884, 2024). "Under pathological conditions such as stroke, astrocytes become reactive, markedly increasing the expression of glial fibrillary acidic protein (GFAP), the hallmark signature of reactive gliosis, in response to intercellular signaling molecules including IL-6, TNFα, TGF-β, INFγ, and IL-10." (PMID 38854014, 2024). "The opposite is true for GFAP, which has demonstrated good sensitivity and specificity in differentiating stroke and haemorrhage, especially when associated with large hematomas, but it cannot accurately determine between ischemic stroke and stroke mimics." (PMID 37511304, 2023). "Future studies involving larger cohorts are required to validate the GFAP and NT-proBNP combined algorithm; however, our study validates the diagnostic utility of blood-based biomarkers in the differentiation of IS and HS in the hyperacute phase of stroke." (PMID 37685295, 2023). "In conclusion, our study strongly suggests that the combination of D-dimer and GFAP with stroke severity scales in a diagnostic algorithm may offer a valuable tool for the early identification of LVO stroke patients." (PMID 34206615, 2021). "In conclusion, different expression of GFAP in IS, HS, and SM suggests it may be a potential biomarker in the diagnosis of hyperacute IS; and GFAP levels were also associated with stroke severity." (PMID 34168606, 2021). "Similarly, patients with the highest GFAP tertile (> 140 pg/mL) were at a risk of both incident stroke (p = 0.01) and ICH (p = 0.009)." (PMID 32321529, 2020). "Further validation of our findings was warranted to see whether NfL and GFAP could serve as biomarkers in identifying patients at risk of stroke." (PMID 32321529, 2020). "Importantly, we also showed for the first time that higher GFAP levels were associated with history of previous episode of stroke." (PMID 27074724, 2016). "Higher GFAP levels were associated with stroke severity and history of prior stroke." (PMID 27074724, 2016). "In summary, we demonstrated elevation of blood UCH-L1 and GFAP early after acute stroke and distinct biomarker-specific release patterns associated with stroke type and characteristics contributing to the current knowledge on the pathophysiology and the role of brain damage markers in acute stroke." (PMID 27074724, 2016). "This leukoencephalopathy is caused by GFAP (glial fibrilary acidic protein) gene mutations and may present with brain stem atrophy and stroke-like onset of symptoms in elderly individuals." (PMID 28035283, 2016). "We report that Rcan1-4 protein and mRNA accumulate in brain cortex early after ischemia/reperfusion, mainly in glial fibrillary acidic protein (GFAP)-positive cells, and that Rcan1 deficiency worsens stroke outcome and increases expression of inflammation-associated genes." (PMID 22397398, 2012).
Stroke (continued). "Transcriptome, protein, and histological analyses all show that old mice have more inflammatory cells, such as CD68+ and GFAP+, than young mice before and after stroke injury, which may cause excessive elimination of synapses and post-stroke memory dysfunction." (PMID 40661422, 2025). "Notably, in patients with AD accompanied by past stroke lesions, plasma GFAP levels may be associated with the severity of cognitive impairment, and plasma NfL levels may reflect the severity of delusions as neuropsychological symptoms." (PMID 40076944, 2025). "As GFAP release kinetics are associated with IS patients’ neurological deficits, it may be used as an additional indicator of functional outcome one month after stroke onset." (PMID 38891912, 2024). "Additionally, GFAP levels might be associated with stroke severity, infarct volumes, bleeding volumes, and stroke location." (PMID 38032374, 2023). "GFAP was correlated with stroke severity (NIHSS, ρ = 0.37-0.40, p < 0.001) and disability (mRS, ρ = 0.48-0.49, p < 0.001)." (PMID 41827388, 2026). "The cellular localization of sigma-1R during stroke progression was identified by co-labeling sigma-1R with neurons (NeuN), astrocytes (GFAP), and microglia (Iba1)." (PMID 41356802, 2026). "Biomarker levels correlated with Field Assessment Stroke Triage for Emergency Destination scores but with limited explanatory power (GFAP R 2=0.077; d-dimer R 2=0.047), suggesting added information beyond clinical severity scales." (PMID 42088320, 2026). "In reactive gliosis, astrocytes typically upregulate GFAP expression in response to brain injury, stroke, and cancer." (PMID 41560805, 2026). "Serum NfL and GFAP represent promising biomarkers for predicting stroke prognosis and tailoring therapeutic strategies." (PMID 41684423, 2026). "Elevated GFAP concentration in serum is also observed following stroke or traumatic brain injury, reflecting general brain damage rather than neoplastic transformation." (PMID 41399659, 2026). "In this study, we aimed to delineate the effects of mono- and combinatorial pre-treatment upon neurological status and biomarkers, namely protein S100b, GFAP, procalcitonin, and galectin-3, following stroke." (PMID 40863995, 2025). "ROC analysis identified an optimal GFAP threshold of 0.57 μg/L for distinguishing intracerebral hemorrhage from ischemic stroke and stroke mimic conditions (AUC 0.871 [95% CI 0.810–0.933], p < 0.001)." (PMID 40066310, 2025). "Future research should focus on combining NSE with other biomarkers (e.g., GFAP, S100B, or inflammatory markers) to improve stroke diagnosis and prognosis, as well as establishing standardized NSE cutoff values for clinical applications." (PMID 40142325, 2025). "More synapses were engulfed by CD68+ microglia/macrophages and GFAP+ reactive astrocytes in the peri-atrophic regions and hippocampi of old stroke mice than young stroke-only mice." (PMID 40661422, 2025). "The old mice had more activated microglia/macrophages (CD68+) and reactive astrocytes (GFAP+) in the peri-atrophic and hippocampal regions ipsilateral to stroke injuries than young stroke mice." (PMID 40661422, 2025). "From 2 to 6 h following stroke onset, serum GFAP was significantly increased in intracerebral haemorrhage patients compared to ischaemic stroke patients." (PMID 39289040, 2025). "GFAP (p < 0.001, Cliff’s d = 0.505) was increased in the stroke patients while AB 40 (p = 0.006, Cliff’s d = 0.363), Aβ 42 (p < 0.001, Cliff’s d = 0.450), and VEGFA (p = 0.005, Cliff’s d = 0.413) where increased in the control patients." (PMID 41306424, 2025). "Statins exhibit neuroprotective properties, reducing GFAP expression in stroke and neurodegenerative diseases." (PMID 40142325, 2025). "This study found GFAP elevated in stroke patients at an acute time point, consistent with previous literature." (PMID 41306424, 2025). "GFAP inclined steeply during the first 3 days after stroke onset, followed by a gradual decline on days 4–7." (PMID 40900222, 2025).